DOCK8 (dedicator of cytokinesis 8)
Description:
Guanine nucleotide exchange factor (GEF) which specifically activates small GTPase CDC42 by exchanging bound GDP for free GTP. During immune responses, required for interstitial dendritic cell (DC) migration by locally activating CDC42 at the leading edge membrane of DC (By similarity). Required for CD4(+) T-cell migration in response to chemokine stimulation by promoting CDC42 activation at T cell leading edge membrane. Is involved in NK cell cytotoxicity by controlling polarization of microtubule-organizing center (MTOC), and possibly regulating CCDC88B-mediated lytic granule transport to MTOC during cell killing.
Synonyms: FLJ00026; FLJ00152; ZIR8; FLJ00346; HEL-205; HIES2; MRD2
Tractability: Antibody: UniProt places it where antibodies can reach, with high confidence; its Gene Ontology location is reachable by antibodies, with high confidence; the Human Protein Atlas places it where antibodies can reach. PROTAC: ubiquitination databases record sites on it; its protein half-life has been measured.
Safety:
Unwanted effects reported when the protein is acted on. In parentheses: how it was acted on, where the effect was seen, and who reports it.
thrombocytopenia (source: ClinPGx)
Gene: Protein-coding gene on chromosome 9 (214,854 to 465,259, forward strand). Ensembl gene ENSG00000107099.
Subcellular location: Cytoplasm; Cell membrane; Cell projection, lamellipodium membrane
Subcellular location (Human Protein Atlas): Cytosol; Plasma membrane
Pathways (Reactome):
Signal Transduction: CDC42 GTPase cycle; RAC1 GTPase cycle; RHOJ GTPase cycle
Hemostasis: Factors involved in megakaryocyte development and platelet production
Gene Ontology:
Molecular function: guanyl-nucleotide exchange factor activity; protein binding
Biological process: cellular response to chemokine; memory T cell proliferation; positive regulation of establishment of T cell polarity; positive regulation of GTPase activity; positive regulation of T cell migration; regulation of Rho protein signal transduction; regulation of small GTPase mediated signal transduction; small GTPase-mediated signal transduction
Cellular component: cytoplasm; cytosol; leading edge membrane; membrane; plasma membrane; cell leading edge; lamellipodium membrane
Genetic constraint (gnomAD): Loss-of-function variants: 126 observed, 234.87 expected, observed/expected ratio (o/e) 0.54, 90% interval 0.46 to 0.62. The upper end of that interval is the gene's LOEUF score, 0.62, which puts it in group 2 of 6, group 1 being the genes least tolerant of losing a copy. Missense variants: 2,896 observed, 2,654.5 expected, observed/expected ratio (o/e) 1.09, 90% interval 1.06 to 1.12. Synonymous variants: 1,147 observed, 993.22 expected, observed/expected ratio (o/e) 1.15, 90% interval 1.1 to 1.21.
Gene-disease validity (ClinGen):
ClinGen rates the evidence that DOCK8 causes each of these diseases.
combined immunodeficiency due to DOCK8 deficiency (autosomal recessive): Definitive. Combined immunodeficiency due to dedicator of cytokinesis 8 protein (DOCK8) deficiency is a form of T and B cell immunodeficiency characterized by recurrent cutaneous viral infections, susceptibility to cancer and elevated serum levels of immunoglobulin E (IgE).
Homologues: Orthologues: macaque DOCK8 (98% identical), chimpanzee DOCK8 (96% identical), pig DOCK8 (94% identical), mouse Dock8 (92% identical), rabbit DOCK8 (92% identical), rat Dock8 (91% identical), guinea pig DOCK8 (89% identical), tropical clawed frog dock8 (74% identical), zebrafish dock8 (67% identical), Drosophila melanogaster Zir (43% identical), Caenorhabditis elegans F46H5.4 (30% identical), Drosophila melanogaster Ziz (27% identical), and 2 more. Paralogues in human: DOCK7 (57% identical), DOCK6 (52% identical), DOCK9 (30% identical), DOCK11 (30% identical), DOCK10 (28% identical), DOCK2 (15% identical), DOCK1 (15% identical), DOCK5 (15% identical), DOCK3 (14% identical), DOCK4 (14% identical).
Diseases named in the same sentence as DOCK8 in open-access papers:
DOCK8 is named in the same sentence as 198 diseases in open-access papers, as found by Europe PMC text mining. Sharing a sentence is not in itself a finding about the gene and the disease. The quoted sentences say what the papers report.
Immunodeficiency (67 papers, 2013 to 2026). Failure of the immune system to protect the body adequately from infection, due to the absence or insufficiency of some component process or substance. "The latest IUIS classification has redefined DOCK8 deficiency as a combined immunodeficiency, and other genes like ZNF341 and components of the IL-6 pathway (IL6ST, IL6R) can cause HIES-like phenotypes." (PMID 41458089, 2025). "DOCK8 is located on chromosome 9 (MIM = 243700), Dedicator of cytokinesis protein 8 (DOCK8) deficiency is currently classified as a combined immunodeficiency." (PMID 40317072, 2025). "Combined immunodeficiencies alongside syndromic characteristics were associated with pathogenic mutations in DOCK8, STAT3, WAS, ATM, and TBX1, which included an autosomal dominant STAT3 variant (c.1144C>T; p.Arg382Trp) and an X-linked WAS variant (c.271C>T)." (PMID 40806973, 2025). "We describe the occurrence of virus PML in a young adult with DOCK8 deficiency—a form of AR-HIES marked by combined immunodeficiency and viral susceptibility." (PMID 41222818, 2025). "In the immune system, defects in GEFs (e.g., Vav1, DOCK8) lead to immune cell dysfunction, resulting in immunodeficiency or autoimmune diseases (e.g., DOCK8 deficiency syndrome)." (PMID 41020039, 2025). "Genetic testing revealed a de novo mutation in the DOCK8 gene, associated with DOCK8 deficiency, a condition usually associated with immunodeficiencies." (PMID 38396937, 2024). "Patients affected by DOCK8 deficiency suffer from combined immune deficiency with severe immune dysregulation." (PMID 39936153, 2024). "The GC B cell loss underlying the humoral defect in DOCK8 immunodeficiency is a consequence of an inability to collaborate with T cells, which is particularly limiting when access to antigen is reduced." (PMID 39121196, 2024). "The most frequent main genetic causes of cellular and humoral immunodeficiencies in children infected with SARS-CoV-2 were DOCK8 deficiency (n = 6), IL2RG (n = 5), RelB deficiency (n = 3), JAK3 deficiency (n = 3), and IL7Ra deficiency (n = 3)." (PMID 37559153, 2023). "Recent studies have shown that DOCK8 mutations can lead to a combined immunodeficiency characterized by severe and persistent viral infections, early‐onset malignancies, and atopic dermatitis." (PMID 37647440, 2023). "DOCK8 deficiency manifests as combined immunodeficiency with recurrent viral, bacterial, and fungal infections, as well as features of immune dysregulation such as eczema, allergies, lymphoproliferation, and autoimmunity." (PMID 37779528, 2023). "Mutations or deletions in the dedicator of cytokinesis 8 (DOCK8) are responsible for autosomal recessive variants of hyper IgE syndrome (HIES) resulting in combined immunodeficiency with severe atopy." (PMID 36839544, 2023). "Dedicator of cytokinesis 8 (DOCK8) deficiency is a rare IEI characterized by a constellation of symptoms including severe immunodeficiency, elevated IgE levels, allergies, and autoimmune disorders." (PMID 38259469, 2023). "Biallelic mutations in the dedicator of cytokinesis 8 (DOCK8) gene were identified as the cause of combined immunodeficiency in 2009." (PMID 37779528, 2023). "DOCK8 deficiency results in immunodeficiency and increased cancer risk, thus supporting that the epigenetic marker for DOCK8 is associated with recurrence in colorectal cancer patients." (PMID 36345336, 2022). "In some patients, cases of immunodeficiency have been reported although the phenotypic spectrum associated with Cdc42 mutations seems wider than that of DOCK8 deficiency." (PMID 35373187, 2022). "Patients with DOCK8 deficiency have a combined immunodeficiency including a susceptibility to virus-induced malignancies." (PMID 35336791, 2022). "Immunodeficiency syndrome, caused by mutations or deletions of the DOCK8 gene, is characterized by persistent microbial infection and increased incidence of malignant tumors." (PMID 36386145, 2022).
Immunodeficiency (continued). "Recessive mutations in DOCK8 have been associated with the hyper immunoglobulin E syndrome which leads to the onset of an immunodeficiency disease combined with other health complications." (PMID 35073835, 2022). "Another study reported that 7 (16.3%) of 43 DOCK8 deficiency patients developed malignant tumors, and the incidence was higher than that of other immunodeficient diseases such as ataxia-telangiectasia and Wiskott-Aldrich syndrome." (PMID 36386145, 2022). "Bi-allelic variants in the dedicator of cytokinesis 8 (DOCK8) gene cause a combined immunodeficiency, characterized by recurrent sinopulmonary and skin infections, food allergies, eczema, eosinophilia, and elevated IgE." (PMID 34080085, 2021). "Autosomal recessive (AR) DOCK8 deficiency is a well-known actinopathy, a combined primary immune deficiency with impaired actin polymerization that results in altered cell mobility and immune synapse." (PMID 34195158, 2021). "DOCK8 deficiency is a combined immunodeficiency due to biallelic variants in dedicator of cytokinesis 8 (DOCK8) gene." (PMID 33936120, 2021). "This cohort of patients did not include patients with DOCK8 mutations in keeping with the fact that DOCK8 deficiency is considered a combined immunodeficiency and hence classified therein." (PMID 33717144, 2021). "Generally, DOCK8 deficiency is characterized by a combination of immunodeficiencies, including recurrent respiratory or skin infections at a young age." (PMID 33787566, 2021). "In humans, loss of function mutations of DOCK8 cause a combined immunodeficiency characterized by recurrent viral infections, severe allergies, autoimmunity, and early-onset malignancy." (PMID 33574036, 2021). "Encountering a child diagnosed with SLE at a very young age, pediatricians should consider immunodeficiency syndrome including DOCK8 deficiency." (PMID 33787566, 2021). "Mutations in human DOCK8 cause a combined immunodeficiency syndrome characterized by allergic diseases such as asthma and food allergy." (PMID 34867940, 2021). "Autosomal recessive hyper-IgE syndrome (AR-HIES) caused by DOCK8 gene is a rare immunodeficiency disease, the main clinical manifestations include recurrent Eczema-like rash, skin and lung abscesses, accompanied with increased serum IgE level." (PMID 34301197, 2021). "Preliminary evidence for this premise is supported by reports of PML cases with mutations in IUIS immunodeficiency disorder genes, such as DOCK8 and STAT1 plus others." (PMID 32256442, 2020). "For example, drastically increased eukaryotic viral colonization was detected in patients with the dedicator of cytokinesis-8 (DOCK8) primary immune deficiency." (PMID 30876458, 2019). "Mutations in the dedicator of cytokinesis 8 (DOCK8) gene cause a combined immunodeficiency extending beyond recurrent infections to include atopy, autoimmunity and cancer." (PMID 30443250, 2018). "Patients with DOCK8 deficiency have a complex combined immunodeficiency secondary to disrupted cytoskeletal rearrangement." (PMID 28674531, 2017). "Mutations of DOCK8 in humans cause a combined immunodeficiency characterized by atopic dermatitis with high serum IgE levels." (PMID 28067314, 2017). "In this report, we describe the challenges of treating a patient with CNS vasculitis in the context of immunodeficiency associated with a DOCK8 gene deletion." (PMID 27113444, 2016). "DOCK2 and DOCK8 physiological relevance has been underscored by the discovery of human-inherited immunodeficiencies caused by DOCK2 or DOCK8 gene mutations." (PMID 26858721, 2016). "Here we reported a patient with atypical DOCK8 deficiency characterized by a much milder phenotype of the immunodeficiency compared to classical DOCK8 deficiency which further broadens the spectrum of DOCK8 associated diseases." (PMID 26680607, 2016). "A further example of immunodeficiency arising form cytoskeletal abnormalities that affect synapse formation is DOCK8 deficiency." (PMID 26379669, 2015).
Immunodeficiency (continued). "Mutations in DOCK8 were found to be the genetic basis of a combined immunodeficiency characterized by increased susceptibility to skin viral infections, hyper IgE syndrome, T cell lymphopenia, and impaired antibody response." (PMID 26379669, 2015). "In 2009, DOCK8 mutations were independently described as the cause of severe immune deficiency in both humans and mice 156,157." (PMID 24117828, 2013). "Interestingly, the bacterium was found in one subject with DOCK8 deficiency, a condition characterized by immunodeficiency affecting both humoral and cellular immunity." (PMID 40150657, 2025). "Aberrations in any regulatory step may lead to diseases, for instance, DOCK8 mutations have been proven to cause immunodeficiency syndromes." (PMID 41020039, 2025). "Beyond immune dysfunction, DOCK8 deficiency may compromise collagen homeostasis, potentially increasing periodontal vulnerability." (PMID 40150657, 2025). "Anti-IL-6 therapy may be beneficial for DOCK8-deficient subjects who prove unresponsive to conventional antiviral chemotherapies, indicating a prospective avenue for clinical management of this immunodeficiency." (PMID 39044832, 2024). "Autosomal recessive DOCK8 deficiency leads to a combined immunodeficiency with many shared features with WAS including atopic dermatitis, food allergies with increased incidence of anaphylaxis, recurrent viral infections, and an increased risk for autoimmunity and malignancies." (PMID 35572516, 2022). "DOCK8 deficiency initially described as the AR form of hyper-IgE syndrome is now classified as a combined immunodeficiency, generally less profound than SCID, but still shares some clinical features with STAT3 deficiency adding to the complexity of the differential diagnosis of HIES with other IEI." (PMID 36703986, 2022). "DOCK8 is notorious because of the immunodeficiency syndrome caused by DOCK8 deficiency." (PMID 36386145, 2022). "Notably, mutations in WAS, WIPF1 or DOCK8 have been reported in human immunodeficiencies, underscoring the importance of these cytoskeleton regulators during immune responses." (PMID 29337666, 2018). "The vast majority of DOCK8-deficient patients present with combined immunodeficiency characterized by recurrent sino-pulmonary and/or gastrointestinal infections, severe cutaneous viral infections, severe atopy, eosinophilia and massively elevated serum IgE levels." (PMID 26680607, 2016). "In addition to immunodeficiency due to defects in upstream regulators (DOCK8), downstream effectors (WASp) of Rho GTPase signaling, immunodeficiency can also result from mutations in the Rho GTPases themselves." (PMID 24117828, 2013). "IEIs included CTLA4HI, APDS, DOCK8, ALPS, DADA2, CVID2, and HA20, with Immune Deficiency and Dysregulation Activity (IDDA) scores of 17-92." (PMID 41634270, 2026). "Dedicator of cytokinesis 8 (DOCK8) immunodeficiency syndrome is characterized by a failure of the germinal center response, a process involving the proliferation and positive selection of antigen-specific B cells." (PMID 39121196, 2024). "In the following section, we summarize essential considerations for gene editing and describe different gene editing strategies and their potential use for correcting DOCK8-mediated immunodeficiency." (PMID 35373187, 2022). "The dedicator of cytokinesis 8 (DOCK8) immunodeficiency syndrome is a severe immune disorder and characterized by serum IgE levels elevation, fungal and viral infections, dermatitis and food allergies." (PMID 36386145, 2022). "Like DOCK8, WASP is critical for DC migration and T-cell priming in vivo, and its deficiency leads to immunodeficiency in humans." (PMID 33574036, 2021). "Mutations in dedicator of cytokinesis 8 (DOCK8) are the major cause of autosomal recessive hyper-IgE syndromes (HIES), which are characterized by combined immunodeficiency and elevated serum IgE levels." (PMID 34867940, 2021).
Immunodeficiency (continued). "Additional genetic defects in MTHFD1, RMRP, CORO1A, PNP, DOCK8, ATM, and BCL11B, among others also cause combined immunodeficiencies, which can be detected by low TREC copy number analysis." (PMID 29713328, 2018). "Dedicator of cytokinesis 8 (DOCK8) deficiency is an autosomal recessive, combined immunodeficiency within the spectrum of hyper-IgE syndromes." (PMID 28293550, 2017). "We report a case of PML in a young adult with autosomal recessive hyper-IgE syndrome (AR-HIES) due to DOCK8 deficiency, highlighting the importance of considering genetic immunodeficiencies in cases of JCV-PML without known iatrogenic or acquired causes." (PMID 41222818, 2025). "Immunodeficiency is a common trait in HIES2 patients, and it is therefore interesting to consider that partially functional DOCK8 variants may generate a spectrum of disorders from HGUS to HIES2 with antibody deficiency as the primary symptom." (PMID 39415980, 2024). "Although dedicator of cytokinesis 8 (DOCK8) deficiency is no longer classified as a HIES but as a combined immunodeficiency, it still should be considered in patients with a HIES clinical phenotype." (PMID 36703986, 2022). "Present evidences suggest that other recently characterized primary immune deficiencies caused by mutation in genes linked to actin cytoskeletal reorganization, such as WIP and DOCK8, may also depend on altered synapse stability." (PMID 26379669, 2015). "Mutations in all three key stages of Rho GTPase signaling have been described in immunodeficiency: the effectors (WASp), the GTPases (Rac2 and RhoH), and the upstream modulators (the Rho/Rac GEF DOCK8), suggesting this pathway is particularly important in immune function." (PMID 24117828, 2013). "For example, a patient with autoinflammatory features may require a selection that favors genes associated with proinflammatory diseases such as MEFVand TNFAIP3, whereas a patient with mainly immunodeficiency may have preferential scoring for genes such as BTK and DOCK8." (PMID 31388879, 2019). "Importantly, no mutations were detected in other known EV-associated or immunodeficiency-related genes, such as RHOH, IL7, CORO1A, STK4, DOCK8, or CARMIL2, supporting the notion that the identified TMC6 and TMC8 variants may represent the primary genetic contributors in this case." (PMID 40534698, 2025). "As expected, our study identified several well-known PADs such as STAT3, WAS, DOCK8, SPINK5, and CARD11 that are classified according to the IUIS as combined immunodeficiency with or without syndromic features." (PMID 35273610, 2022).